MTOR (mechanistic target of rapamycin kinase)
Diseases named in the same sentence as MTOR in open-access papers (continued):
Sharing a sentence is not in itself a finding about the gene and the disease.
neuroblastoma (continued). "Therefore, the feedback regulation between mTOR-S6K signaling and MYCN/NCYM may contribute to the survival of MYCN-amplified neuroblastoma cells." (PMID 24391509, 2014). "Among neurologic tumors, in neuroblastoma (NB), lncRNA MEG3 functions as an anti-tumor agent, and overexpressing MEG3 in NB cells decreased epithelial-mesenchymal transition invasion and metastasis via mTOR signaling and inhibited FOXO1-mediated autophagy." (PMID 38933333, 2024). "Thus, autophagy-mediated cell death in neuroblastoma is independent of the AKT/mTOR axis." (PMID 32943619, 2020). "The same work further suggests that monotherapy consisting of PI3K/mTOR inhibition alone is ineffective in neuroblastoma that do not harbor a MYCN amplification, which led us to speculate that NVP-BEZ235 might be better suited as part of a targeted combination therapy." (PMID 24391739, 2013). "Here, in this paper, we for the first time show that the iron chelator VLX600 inhibits mitochondrial respiration, decreases mTOR activity, reduces the expression of MYCN/LMO1 and induces an efficient cell death regardless of MYCN statues in neuroblastoma cells." (PMID 35805002, 2022). "Our results indicate that PI3K inhibitors with weak activity against mTOR fail to target MYCN protein, implying that activity of the PI3K complex may not play a major role in stabilization of MYCN protein in neuroblastoma cells." (PMID 27438153, 2016). "Additionally, the PI3K/mTOR inhibitor PI103 induced time- and concentration-dependent inhibition of cell growth in both MYCN and non-MYCN amplified neuroblastoma cell lines." (PMID 25134527, 2014). "Moreover, inhibitors of PI3K/mTOR and GLI signaling reduced neuroblastoma cell growth, but no additional growth inhibitory effects were detected when the two classes of drugs were combined." (PMID 25134527, 2014).
diabetic nephropathy (165 papers, 2011 to 2026). "Multi-cohort (CRIC/SMART2D/American Indian) studies established UAdCR as a mechanistic ESKD biomarker; proximal tubule mTOR signaling underlies normoalbuminuric pathology.Dysregulated autophagy drives diabetic kidney disease (DKD) progression." (PMID 40337513, 2025). "To further investigate the regulatory role of TCF3 in autophagy, we examined the expression of proteins associated with the PI3K/Akt/mTOR signaling pathway in renal tissues of diabetic nephropathy rats via Western blotting." (PMID 41404576, 2025). "Of interest, the top diabetes nephropathy-associated pathways of most of the extracellular vesicles key miRNAs families were related to Wnt signaling, mTOR, ErbB signaling, PI3K-Akt, and calcium signaling." (PMID 38966710, 2024). "It has been demonstrated that mTOR is significantly overexpressed and activated in diabetic nephropathy and that hyperactivated mTOR causes podocyte loss." (PMID 39265079, 2024). "A similar effect was observed in a model of diabetic kidney disease, where Klotho gene deficiency enhanced the phosphorylation of the mammalian target of rapamycin (mTOR) and protein p70 ribosomal protein S6 kinase (p70S6K) in the kidney." (PMID 37699938, 2023). "There is a growing body of evidence indicating that mTOR inhibitors are the preferred treatment for diabetic nephropathy, which is primarily associated with reduced proteinuria and albuminuria." (PMID 34627341, 2021). "mTOR activation underlies glomerular hypertrophy in diabetic nephropathy and chronic kidney disease, and mTOR inhibition prevents diabetic glomerular hypertrophy." (PMID 32597007, 2020). "Previously some evidences have been obtained regarding dysregulation of mTOR signaling in some prevalent kidney diseases like diabetic nephropathy and cystic kidney disease and the association of increased fibrosis with mTOR in chronic kidney disease." (PMID 31658846, 2019). "A previous study indicated that the mTOR pathway has an important pathogenic role in diabetic nephropathy." (PMID 31485275, 2019). "In conclusion, the potential nephroprotective effects of MSC-derived exosomes in a diabetic nephropathy model are based on their ability to upregulate autophagy associated with suppression of mTOR pathway, and by their antifibrotic effect." (PMID 30467302, 2018). "There is increasing evidence that the mTOR (mammalian target of rapamycin) pathway is involved in the pathogenic manifestations of diabetic nephropathy." (PMID 23936373, 2013). "In addition to the changes in metabolic phenotype, diabetic nephropathy is also associated with increased apoptosis and increased mTOR, and possibly AhR, signaling." (PMID 39902076, 2024). "As Nox4/AMPK/mTOR signaling has been reported to be implicated in diabetic kidney disease, we hypothesized that the AMPK/mTOR signaling might be implicated in Nox4-mediated regulation of HG-induced injury." (PMID 35813614, 2022). "It has been postulated that hyperfiltration in patients with TSC is caused by overactivation of the mTOR pathway in the glomerulus and, as in diabetic nephropathy, may be a risk factor for progression of renal disease." (PMID 34912759, 2021). "They demonstrated that complete reduction of mTORC1 in RaptorΔpodocyte mice resulted in proteinuria and the progression of diabetic nephropathy, while deletion of only one allele of Raptor (RaptorHet podocyte) inhibited mTOR activation, leading to decreased proteinuria and glomerulosclerosis." (PMID 32444668, 2020). "Additionally, overactive mTOR is linked to aging and diabetic nephropathy, and mTOR inhibitors are beneficial for a number of renal diseases." (PMID 28351995, 2017). "Although the precise mechanism remains unclear, involvement of innate immunity in the early stage of diabetic nephropathy associated with mTOR was reported." (PMID 27338360, 2016).
diabetic nephropathy (continued). "In addition, a causal link between the activation of the mTOR pathway and the progression of polycystic kidney disease or diabetic nephropathy was reported." (PMID 27338360, 2016). "Activation of mTOR within the kidney has been reported in different kinds of kidney diseases, including acute ischemic injury, polycystic kidney disease, diabetic nephropathy and other causes of progressive kidney disease." (PMID 22470459, 2012). "Triptolide targets autophagy through the mTOR/Twist1 pathway and inhibits the epithelial-mesenchymal transition of podocytes in diabetic nephropathy." (PMID 41536046, 2025). "This study unveils a new role of HU in alleviating diabetic kidney disease by modulating inflammation and apoptosis through the mTOR-S6K pathway." (PMID 39911324, 2025). "Dapagliflozin enhances AMPK activity while inhibits the mTOR pathway, thereby bolstering podocyte autophagy in diabetic nephropathy." (PMID 41353143, 2025). "In sum, this study unveils a new role of HU in alleviating diabetic kidney disease by modulating inflammation and apoptosis through the mTOR-S6K pathway." (PMID 39911324, 2025). "Hyperactivation of mTOR in podocytes leads to diabetic nephropathy and premature death in mice, which can be preventable by treatment with rapamycin." (PMID 39859520, 2025). "Prior research has demonstrated a robust correlation between the mammalian target of rapamycin (mTOR) and diabetic kidney disease." (PMID 40141229, 2025). "Of note, mTOR is regarded as an endogenous inhibitor of autophagy and was reported to increase the progression of diabetic nephropathy." (PMID 39656379, 2024). "LC3‐II was examined, and Beclin1 expressed by MSCs can inhibit the mTOR pathway, which promotes renal TEC autophagy and improves renal fibrosis caused by diabetic nephropathy." (PMID 38898750, 2024). "The phosphatidylinositol 3-kinases/protein kinase B/mammalian target of the rapamycin (PI3K/AKT/mTOR) signaling pathway plays an essential role in the implementation of the high glucose effect in diabetic kidney disease and renal fibrosis." (PMID 38540101, 2024). "DDIT4 is an important target of VDR/mTOR/p70s6k/4E-BP1 signaling pathway induced by high glucose in diabetic nephropathy." (PMID 38567351, 2024). "A growing body of evidence indicates the role of the PI3K/AKT/mTOR signaling pathway in the pathogenesis of diabetic kidney disease." (PMID 38540101, 2024). "In their study, mTOR mRNA and protein levels were significantly upregulated in mice with diabetic nephropathy and were significantly reduced by the infusion of MSC‐derived exosomes into the mice." (PMID 38898750, 2024). "An important intermediate in the cascade leading to diabetic nephropathy, mammalian target of rapamycin (mTOR), can be inhibited by use of rapamycin." (PMID 38790940, 2024). "Smad1/mTOR signaling transduction is involved in autophagy dysfunction-mediated podocyte injury, and hyperactivation of mTOR in diabetic nephropathy plays a fundamental role in podocyte injury." (PMID 38988671, 2024). "Located in the glomerular podocyte and mesangial cell, mTOR is involved in the generation of diabetic nephropathy." (PMID 37759585, 2023). "The possible involvement of AMPK, MAPK, and mTOR pathways in the protective effects of CMS121 against diabetic nephropathy is an interesting topic for future study." (PMID 37047807, 2023). "Long-term or excessive albumin in glomerular filtrate of diabetic nephropathy patients can eventually impair autophagy of PTECs through mTOR dependent mechanism, leading to tubular injury." (PMID 36942026, 2023). "Knockout of the tsc1 gene (which negatively regulates the mTOR factor) in mice resulted in increased endoplasmic reticulum stress and eventually diabetic nephropathy." (PMID 37108143, 2023).
diabetic nephropathy (continued). "In rat retinal microvascular endothelial cells, it was found that under high‐glucose stimulation, mTOR pathway activation mediated the epithelial–mesenchymal transition and promoted the progression of diabetic nephropathy." (PMID 36890627, 2023). "The key upstream regulators of autophagy, such as mTOR, are involved in the pathogenesis of diabetic nephropathy." (PMID 37108143, 2023). "In mice, it was shown that intervention with rapamycin (an mTOR inhibitor) inhibited the development of diabetic nephropathy by enhancing autophagy in podocytes." (PMID 37108143, 2023). "Bergenin hinders the production of extracellular matrix in glomerular mesangial cells and mitigates diabetic nephropathy in mice by suppressing oxidative stress through the mTOR/β-TrcP/Nrf2 pathway." (PMID 37375124, 2023). "Antidiabetics, like Metformin, evidenced lower podocyte destruction, mesangial cells apoptosis and tubulointerstitial cell senescence via AMPK and mammalian target of rapamycin (mTOR) regulation in diabetic nephropathy." (PMID 37762322, 2023). "Butyrate ameliorates skeletal muscle atrophy in diabetic nephropathy rats by enhancing FFA2-mediated PI3K/Akt/mTOR signals." (PMID 36196075, 2022). "The progression of diabetic nephropathy is also influenced by oxidative stress, lipid metabolism, and mTOR activation." (PMID 35251009, 2022). "Thioredoxin-interacting protein (TXNIP) takes charge of regulating the autophagy of rats with diabetic nephropathy via the mTOR signaling pathway." (PMID 36591291, 2022). "LncRNA NEAT1 activated Akt/mTOR pathway and accelerated cell fibrosis and proliferation in diabetic nephropathy." (PMID 36313695, 2022). "In recent years, the role of the PI3k/Akt/mTOR signaling pathway in the development of diabetic nephropathy has received increasing attention." (PMID 35299891, 2022). "Inhibiting the mTOR pathway can prevent the early structural alterations in the renal tissues developing towards diabetic nephropathy." (PMID 35620059, 2022). "Paecilomyces cicadae-fermented Radix Astragali can enhance the autophagy of podocytes in diabetic mice by inhibiting the PI3K/AKT/mTOR signaling pathway, thereby reducing podocyte apoptosis and improving the renal structure of diabetes nephropathy." (PMID 36003509, 2022). "Differentially expressed marker genes of immune cells EIF4B, RICTOR, and PRKCB were significantly enriched in the mTOR pathway, which were confirmed to be up-regulated in diabetic nephropathy." (PMID 35620059, 2022). "MALAT1 aggravates renal tubular epithelial injury by interacting with LIN28A to activating the Nox4/AMPK/mTOR signaling in rats with diabetic nephropathy." (PMID 35813614, 2022). "With the progression of kidney disease, the expression of klotho protein in patients with diabetic nephropathy decreases, and the decrease of klotho can activate the mTOR signaling pathway and aggravate kidney damage." (PMID 35692885, 2022). "Its downstream effectors play a key role in cell growth and hypertrophy, while the inhibition of mTOR by rapamycin can prevent the development of diabetic nephropathy in animals with type 1 and type 2 diabetes." (PMID 35299891, 2022). "The possible explanation is that metformin regulates the mTOR pathway by upregulating klotho and protects renal tubular cells, thereby delaying renal progression in patients with diabetic nephropathy." (PMID 35692885, 2022). "This was confirmed by the findings that insufficient lysosomal replenishment and damaged lysosomal clearance coincided with TFEB inactivation, which was mediated by mTOR hyperactivation in the renal tubular epithelial cells (TECs) of diabetic nephropathy." (PMID 35082964, 2022). "MALAT1 activated LIN28 and Nox4/AMPK/mTOR pathway, resulting in promotion of renal tubular injury in diabetic nephropathy." (PMID 36313695, 2022).
diabetic nephropathy (continued). "Recent studies have shown that in DKD, tripterygium glycoside attenuates EMT and apoptosis in diabetic kidney disease, by upregulating autophagy through the mTOR/Twist1 signalling pathway." (PMID 35560773, 2022). "Mesenchymal stem cell-derived exosomes ameliorated diabetic nephropathy by autophagy induction through the mTOR signaling pathway." (PMID 36684427, 2022). "It has been reported that GLP-1 alleviates diabetic kidney disease by significantly decreasing urinary albumin and ameliorating renal pathological changes in vivo, and improves autophagy through mTOR signaling pathway." (PMID 34349660, 2021). "Arbutin (ARB) has been associated with protecting HK-2 cells against high-glucose-induced apoptosis and autophagy in diabetic nephropathy (DN) through regulating the miR-27a/JNK/mTOR axis." (PMID 34361788, 2021). "In glomerular extracts from biopsies of FSGS and diabetic nephropathy mammalian target of rapamycin (mTOR) and PEC-activation related genes were found to be upregulated." (PMID 35095882, 2021). "mTOR signaling has been shown to be physiologically and pathologically critical in diabetic kidney disease." (PMID 34627341, 2021). "On the contrary, resveratrol alleviated diabetic nephropathy conditions by attenuating oxidative stress and insulin resistance and augmenting AMPKα/mTOR-mediated autophagy induction in STZ-induced diabetic rats." (PMID 34681206, 2021). "mTOR, a serine/threonine kinase, is regulating the cell growth and inhibited mTOR activity to strengthen autophagy in diabetic nephropathy." (PMID 33204708, 2020). "For example, the saponin astragaloside IV (AS-IV) and the polyphenol glucoside mangiferin prevented podocyte injury through AMPK/mTOR regulated autophagy in a model of streptozotocin-induced diabetic nephropathy." (PMID 31936109, 2020). "An adipokine, apelin, that promoted podocyte injury and the progression of diabetic nephropathy in kkAy mice, inhibited autophagy in podocytes through activating the mTOR pathway." (PMID 31936109, 2020). "Another potential mechanism of podocyte dysfunction in diabetic nephropathy is the regulation of mTOR activity." (PMID 33303821, 2020). "It is well documented that PI3K-Akt-mammalian target of rapamycin (mTOR) signaling pathway plays a key role in matrix protein synthesis during diabetic kidney disease, since blockade of this pathway ameliorates renal injury in diabetic rodent models." (PMID 31390847, 2019). "Thioredoxin interacting protein (TXNIP), which induces ROS production, regulated tubular autophagy and mitophagy in a rat model of diabetic nephropathy through the mTOR signaling pathway." (PMID 31382550, 2019). "Recent research has shown that dysregulation of the mechanistic target of rapamycin (mTOR) has a role in certain common kidney diseases, such as diabetic nephropathy and polycystic kidney disease." (PMID 30873046, 2019). "Among them, the activation of mammalian target of rapamycin (mTOR) signaling pathway is involved in the pathogenesis for several kidney diseases, such as diabetic nephropathy." (PMID 29326403, 2018). "In the kidney, mTOR regulates normal renal function, and dysregulation of mTOR signaling contributes to kidney diseases like diabetic nephropathy and cystic kidney disease." (PMID 28831205, 2017). "Analysis of mRNA extracted from the microdissected glomeruli of patients with glomerulopathies showed that expression of mTOR mRNA and mTORC1 target genes increased in very early diabetic nephropathy." (PMID 27338360, 2016). "Dysregulation of the Akt pathway and its downstream cascades, including mTOR, NFκB, and Erk1/2, play a critical role in the development of diabetic nephropathy." (PMID 27585918, 2016). "This review discusses the role of mTOR inhibitors in renal disease with a particular focus on renal cancer, diabetic nephropathy, and kidney transplantation." (PMID 27338360, 2016).